VEGFA (vascular endothelial growth factor A)
Diseases named in the same sentence as VEGFA in open-access papers (continued):
Sharing a sentence is not in itself a finding about the gene and the disease.
esophageal cancer (77 papers, 2010 to 2025). A primary or metastatic malignant neoplasm involving the esophagus. "Recently, several studies reported that VEGFA was associated with esophageal cancer development." (PMID 38429756, 2024). "The downregulation of miR-375 contributes to ERBB2-mediated VEGFA overexpression in esophageal cancer." (PMID 37397256, 2023). "To further explore the downstream signaling of miR-516b-5p involved esophageal cancer cell growth and mobility, the target genes were predicted by miRDB and TargetScan databases and we found that VEGFA was a potential target of miR-516b-5p." (PMID 35681693, 2022). "Collectively, these results suggest that JPX promoted esophageal cancer cell growth and mobility via miR-516b-5p/VEGFA signaling pathway." (PMID 35681693, 2022). "TUSC8 inhibits the proliferative and migratory abilities in esophageal cancer cells in vitro by negatively regulating VEGFA." (PMID 34659529, 2021). "VEGFA is one of the essential growth factors for tumor angiogenesis in endothelial cells, and higher VEGFA expression as a marker indicating that an advanced stage with a poor OS for patients with esophageal cancer." (PMID 32662828, 2020). "Overexpression of VEGFA could reverse the regulatory effects of TUSC8 on esophageal cancer cell proliferation and migration." (PMID 34659529, 2021). "Finally, the co-regulation of TUSC8 and VEGFA on esophageal cancer cell functions was evaluated." (PMID 34659529, 2021). "In Esophageal Cancer high levels of exosomal circZNF609 promote metastasis and angiogenesis, partly by regulating the circ-ZNF609/miR-150-5p/VEGFA axis and the HuR/ZO-1 axis." (PMID 41301888, 2025). "In this study, we found ERK phosphorylation, VEGFA and MMP3 were also inhibited after MAP4 knockdown, further confirmed that MAP4 played an important role in promoting esophageal cancer." (PMID 36991467, 2023). "VEGFA, FOSL1, MAOB, SDR16C5, RP11-58O9.2, RP11-667F14.1, and RP11-288A5.2 may be served as genetic targets for preventing stent restenosis in esophageal cancer." (PMID 33391336, 2020). "DE VEGFA, FOSL1, MAOB, SDR16C5, RP11-58O9.2, RP11-667F14.1, and RP11-288A5.2 in hyperplastic tissues may serve as genetic targets for preventing stent restenosis in esophageal cancer." (PMID 33391336, 2020).
ovarian tumor (77 papers, 1997 to 2026). "Elevated levels of VEGFA in ovarian tumors have been linked to advanced disease stages and reduced survival rates." (PMID 37964873, 2023). "They showed an increased level of the VEGFA protein associated with the ovarian tumor stage." (PMID 36230822, 2022). "We also reveal that anti-VEGFA intervention controls ovarian tumor growth by increasing SELENOP+ macrophages and cytotoxicity of CD8+ T cells in vivo." (PMID 41526347, 2026). "The same tendency was shown in ovarian tumors, and VEGFA expression intensified with the pathological process progress." (PMID 39888575, 2026). "The pro-angiogenic macrophage subpopulation (Mac_Angio, n = 3108) displayed high expression of genes associated with angiogenesis, such as VEGFA, VCAN, and EREG, and was found enriched in lung and ovarian tumors." (PMID 38972873, 2024). "ID8-Defb29/Vegf-A is a highly aggressive ovarian tumor cell line that overexpresses mouse vascular endothelial growth factor-A (Vegf-A164) and β-defensin-29 (Defb29)." (PMID 38832992, 2024). "Effects of VEGFA and Bmi1 on ovarian tumor‐initiating cell abundance were further investigated in vivo." (PMID 28179359, 2017). "We show that endothelial FABP4 expression requires NOTCH1 and VEGFA signalling, and is required for ovarian tumour angiogenesis." (PMID 27568980, 2017). "BMI1 knockdown abolished VEGFA‐dependent increases in sphere formation and in ovarian tumor‐initiating cells in vivo." (PMID 28179359, 2017). "ELISA analyses demonstrated that both drugs strongly inhibited the secretion of VEGFA in ovarian tumor cells (A2780 cells; MTA: 2.39-fold, DIG-MSK: 2.55-fold, p<0.05; OVCAR-3 cells; MTA: 2.40-fold, DIG-MSK: 3.44-fold, p<0.05)." (PMID 26536461, 2015). "ZNF385B, previously unrecognized as a potential ovarian tumour marker, and VEGFA correlated with overall and progression-free survival, respectively, whereas TPX2 and FOXM1 with optimal CA125 normalization." (PMID 23029477, 2012). "In addition, suppression of VEGFA activation may enhance the therapeutic effectiveness of ovarian tumour chemotherapy through inhibition of autophagy related to VEGFA." (PMID 35464051, 2022).
renal fibrosis (77 papers, 2013 to 2025). A final common manifestation of a wide variety of chronic kidney diseases characterized by glomerulosclerosis and tubulointerstitial fibrosis. "COL4A2, CXCL1, TIMP1, VCAM1, and VEGFA are promising diagnostic biomarkers of tissue and serum for renal fibrosis." (PMID 37266443, 2023). "In short, COL4A2, CXCL1, TIMP1, VCAM1, and VEGFA are promising diagnostic biomarkers of tissue and serum for renal fibrosis, which is helpful for the early diagnosis and treatment of patients with renal fibrosis." (PMID 37266443, 2023). "Five genes (COL4A2, CXCL1, TIMP1, VCAM1, and VEGFA) were subsequently identified as biomarkers for renal fibrosis through machine learning, and their expression levels were confirmed by validation cohort data sets and in vitro RT-qPCR experiment." (PMID 37266443, 2023). "In injured tissue, angiogenesis was stimulated by various proangiogenic mediators, including VEGFA and transient upregulation of VEGFA expression was detected during renal fibrosis progression (p < 0.05)." (PMID 34645813, 2021). "Our research clarified the downregulation of VEGFA expression in renal fibrosis." (PMID 37266443, 2023). "VEGFA plays a key role in the progression of renal fibrosis." (PMID 35129424, 2022). "Although it has been reported that impaired expression of VEGFA in hepatic, pulmonary or renal fibrosis further aggravates fibrotic phenotypes and poor prognoses, the functions and mechanisms of VEGFA in endometrial fibrosis remain unclear." (PMID 31515487, 2019). "To study SSLF's functional mechanism and understand its potential inhibitory role in renal fibrosis, first, we found that STAT3, VEGFA, and AKT1 of the intersection genes of SSLF and RIF are the core proteins in the intersection genes." (PMID 35399631, 2022). "VEGFA, as a growth factor essential for angiogenesis, inhibits the expression of Smad3 and miR192, thereby suppressing IGF-β-induced endothelial interstitial transformation and ameliorating renal fibrosis." (PMID 37404805, 2023). "Moreover, comprehending the roles of VEGFA and BTG1 in renal fibrosis may open the door to personalized treatment approaches." (PMID 37949939, 2023). "Indeed, according to the literature, there is a correlation between the histopathological evidence of renal fibrosis and profibrotic renal tissue markers, such as transforming growth factor-β1 (TGF-β1), connective tissue growth factor (CTGF), and vascular endothelial growth factor A (VEGF-A)." (PMID 36176443, 2022).
metabolic syndrome (76 papers, 2009 to 2025). A cluster of metabolic risk factors for CARDIOVASCULAR DISEASES and TYPE 2 DIABETES MELLITUS. "Future studies will investigate the mechanistic role of VEGFA expressed in PBMCs in response to HCHF diet, in relation to atherogenesis, and whether VEGFA is a potential biomarker for dyslipidemia." (PMID 30875406, 2019).
clear cell renal cell carcinoma (75 papers, 2006 to 2025). "Clear cell renal cell carcinoma (ccRCC) is known for its highly vascular phenotype which is associated with elevated expression of vascular endothelial growth factor A (VEGF), also known as vascular permeability factor (VPF)." (PMID 31840081, 2019). "VEGFA may be a prognostic gene in clear cell renal cell carcinoma, as significant increases in VEGFA are associated with a poor prognosis." (PMID 34217310, 2021). "Clear cell renal cell carcinoma (ccRCC) patients are highly angiogenic and treated by targeted therapies against VEGFA/VEGFR signaling pathway." (PMID 35562342, 2022). "In clear-cell renal cancer, eight differentially expressed genes were identified as biomarkers, including VEGFA, FLT1, FN1, and others." (PMID 32070055, 2020). "miR-185 can inhibit cell proliferation and increase apoptosis by regulating VEGFA in clear cell renal cell carcinoma." (PMID 32492657, 2020). "Also, miR-185 was found to inhibit cell proliferation and induce apoptosis by targeting VEGFA directly in von Hippel-Lindau-inactivated clear cell renal cell carcinoma." (PMID 33224264, 2020). "In F107 case, interestingly, amplification of VEGFA and CCND3 on chromosome 6 was observed, which may lead to the formation of clear cell renal cell carcinoma." (PMID 37182269, 2023).
chronic kidney disease (74 papers, 2011 to 2026). Impairment of the renal function secondary to chronic kidney damage persisting for three or more months. "Vascular Endothelial Growth Factor A (VEGFA) is associated with an increased risk of chronic kidney disease but induces vasculogenesis." (PMID 36482897, 2022). "Previous genomic studies have reported that patients with wild-type (G allele) rs881858 were associated with chronic kidney disease development due to decreased nephrogenesis, which is induced by reduced VEGFA activity." (PMID 34200782, 2021). "Chronic kidney disease is strongly associated with a decrease in the expression of vascular endothelial growth factor A (VEGF‐A)." (PMID 28574576, 2017). "These authors showed that miR-20a-5p affects VEGFA signaling pathways, which are involved in osteoblast differentiation and angiogenesis, as well as the development of chronic kidney disease." (PMID 40004454, 2025). "In a chronic kidney disease (CKD) rat model, miR-17-5p has also been identified as a calcification-protective miRNAs that targets vascular endothelial growth factor A (VEGFA) signaling in CKD-driven vascular calcification." (PMID 41303301, 2025).
macular degeneration (72 papers, 2008 to 2025). Loss of vision in the central portion of the retina (macula), secondary to retinal degeneration. "In fact, VEGFA overexpression is one of the main causes of macular degeneration, leading to new blood vessel formation and visual acuity loss." (PMID 41007164, 2025). "Secretion of VEGFA (vascular endothelial growth factor A) from RPE cells is pathogenic in macular degeneration and arises in part through the cytokine Transforming Growth Factor β (TGFβ), which also changes the migratory and adherent capacity of RPE cells." (PMID 35806007, 2022). "VEGFA plays an important role in the pathophysiology of macular degeneration." (PMID 41007164, 2025). "Therefore, developing a new VEGFA inhibition strategy for treating macular degeneration is important." (PMID 41007164, 2025). "Related research and development of exosome-based VEGFA siRNA delivery are garnering attention as a promising approach that can overcome the limitations of existing treatments and are expected to provide new possibilities for the treatment of macular degeneration." (PMID 41007164, 2025). "Therefore, VEGFA inhibition is considered a major strategy for treating macular degeneration." (PMID 41007164, 2025). "Anti-VEGF drugs have been related to variable response depending on CXCL8, VEGFA, NRP1, ARMS2, CFH, and HTRA1 genotypes in macular degeneration and depending on VEGFA genotype in CNV patients, without differentiating results among PCV patients." (PMID 33198211, 2020).
head and neck squamous cell carcinoma (69 papers, 2003 to 2025). A squamous cell carcinoma that arises from any of the following anatomic sites: lip and oral cavity, nasal cavity, paranasal sinuses, pharynx, larynx, and salivary glands. "IGF2BPs also enhanced VEGFA expression in head and neck squamous cell carcinoma and pancreatic ductal adenocarcinoma, potentially promoting immunosuppressive signaling." (PMID 41049442, 2025). "In turn, hsa-miR-99a-3p was downregulated in head and neck squamous cell carcinoma, and VEGFA was reported to be the main target gene for hsa-miR-99a-3p." (PMID 35743538, 2022). "A close expression among molecules associated with angiogenesis: p-STAT3, VEGFA, CK2, and the MDSCs marker CD11b was found in head and neck squamous cell carcinoma (HNSCC) patients." (PMID 31057536, 2019). "Interestingly, bevacizunb (a neutralizing antibody against VEGFA) has entered into phase II clinical trials for head and neck squamous cell carcinoma treatment." (PMID 27541266, 2016). "A groundbreaking report confirmed that high expression of CAF-specific VEGFA, PGE2S, COX2, EGFR, CCL2, and NANOG was considered as the culprit of CDDP resistance development in head and neck squamous cell carcinoma (HNSCC)." (PMID 36359776, 2022). "Ectopic expression of miR-34a in human head and neck squamous cell carcinoma (HNSCC) cells was found to inhibit tumor growth and angiogenesis that was partially reversed by blocking VEGFA production by tumor cells." (PMID 29293555, 2018). "Moreover, VEGFA, VEGFB, VEGFC, and PGF expression was significantly increased in CHOL, head and neck squamous cell carcinoma (HNSC), KIRC, and LIHC tumor tissues." (PMID 37852616, 2023). "Vascular endothelial growth factor A (VEGF-A), stromal cell-derived factor 1 (SDF-1), and platelet-derived growth factor (PDGF) are examples of such migratory attractants, the latter being assumed to be involved in the migration of hMSCs towards head and neck squamous cell carcinoma (HNSCC)." (PMID 34204818, 2021). "Indeed, several researches has reported that ALDOA and PGK1 also mediated in OSCC and head and neck squamous cells carcinoma (HNSCC).Ahluwalia also reported that HIF-1 under hypoxic conditions regulates the expression of vascular endothelial growth factor A (VEGFA) at the transcriptional level." (PMID 33941139, 2021).
fibrosis (68 papers, 2006 to 2026). the formation of excess fibrous connective tissue in an organ or tissue in a reparative or reactive process. "On the other hand, some studies have shown that increased VEGFA in certain development of fibrosis condition." (PMID 37266443, 2023). "Among these genes, the expression of inflammation-associated FCER1G, OSM, VEGFA, and ZAP70 was lower in high-grade fibrosis than in low-grade fibrosis, whereas CHIT1 expression, which is associated with fibrogenic activity of macrophages, was higher in high-grade fibrosis." (PMID 35052861, 2022). "Moreover, in the NAFLD-HCC group, a positive link between hepatic fibrosis and VEGFA was observed." (PMID 38751599, 2024). "In our study, VEGFA and CXCL8, in conjunction with CDKN1A, were the most upregulated genes in fibrosis patients." (PMID 37569323, 2023). "Hence, VEGFA, CXCL8, and CDKN1A, with a mild tendency to be upregulated in fibrosis patients, were markedly induced in the hyperfibrosis ones, with more pronounced signs of conjunctival fibrosis and very early failure of filtering surgery." (PMID 37569323, 2023).
oral cancer (68 papers, 2009 to 2025). "Research from our group suggested that VEGFA stimulated OSCC and oral cancer- associated fibroblast cell migration and can be inhibited by a specific PI3 kinase and mTORC2 inhibitor." (PMID 38002001, 2023). "Knockout of HSD11B2 promoted tumor angiogenesis (expression of EGFR and VEGFA), cell proliferation, and invasion in oral cancer cells." (PMID 36631756, 2023). "This study demonstrated that CERS1 knockdown was associated with endoplasmic reticulum (ER) stress and upregulated vascular endothelial growth factor A (VEGFA), which promoted oral cancer aggressiveness and chemotherapy drug resistance." (PMID 35954376, 2022).
viral infection (68 papers, 2009 to 2026). "The upregulation of GLUT1 and VEGFA in SARS-CoV-2-infected cells suggest the activation of a hypoxia-associated signaling upon viral infection." (PMID 34185793, 2021). "In recent years, increased levels of VEGFA have been observed in pro-inflammatory environments created by viral infections in humans, further motivating study of VEGFA." (PMID 30849965, 2019). "Assuming a link between angiogenesis and inflammation, the role of VEGFA in viral infectious diseases, especially in haemorrhagic lesions, has been explored." (PMID 30849965, 2019). "This is possibly due to a positive feedback between DENV and HIF, because viral infection increases the expression of the HIF-target gene VEGFA and upregulates HRE activation." (PMID 30513781, 2018). "However, the obese and obese with T2D cohorts enriched for less relevant terms such as nervous system development and viral infection pathways (although the obese cohort is also enriched for VEGFA-VEGFR2 signaling)." (PMID 37961160, 2023). "Viral infection also increased the expression of the antioxidant genes NRF2 and HO-1, as well as of VEGFA, as shown by comparing mock-treated infected to mock-infected cells, along with already published reports." (PMID 34834946, 2021). "As a result, we hypothesized that JUN, VEGFA, TNFSF10, and TLR4 in PBMC can also regulate virus infection of HCC patients." (PMID 31531018, 2019).
nasopharyngeal carcinoma (66 papers, 2006 to 2025). A carcinoma arising from the nasopharyngeal epithelium. "A high ratio of tumor-suppressive TNF+/vascular endothelial growth factor A (VEGFA)+ MC phenotype is found in nasopharyngeal cancer in the patients." (PMID 36189267, 2022). "MiR-15b-5p and miR-16-5p, which are located in the same cluster on chromosome 3, were down-regulated following hypoxia in human nasopharyngeal carcinoma cells, promoting VEGFA expression, which ultimately facilitated angiogenesis." (PMID 34947800, 2021). "The regulation between FBXW7 and VEGFA was also confirmed in nasopharyngeal carcinoma." (PMID 36991467, 2023). "In nasopharyngeal carcinoma, lncRNA HOTAIR promotes angiogenesis via GRP78-mediated upregulation of VEGFA and ANG2 expression." (PMID 32993787, 2020). "In nasopharyngeal carcinoma, EBV-induced angiogenesis mimicry is primarily achieved through the PI3K/AKT/mTOR/HIF-1α/VEGFA signaling cascade." (PMID 32993787, 2020). "In nasopharyngeal carcinoma (NPC) HOTAIR is strongly up-regulated in cell lines and tissues, and its knockdown leads to a significant decrease of several angiogenic factors, such as vascular endothelial growth factor A (VEGFA) and angiopoietin 2 (Ang2)." (PMID 31072041, 2019).
Pleural effusion (63 papers, 2006 to 2025). The presence of an excessive amount of fluid in the pleural cavity. "Traditional pathways of angiogenesis have been suggested as targets for therapy due to adverse prognostication associated with increased serum and pleural effusion levels of the pro-angiogenic marker vascular endothelial growth factor A (VEGFA)." (PMID 29104239, 2017). "Increased levels of VEGFA in pleural effusions were associated with poor survival." (PMID 29085180, 2017). "To further investigate prognostic implications within our cohort and investigate the potential role of BAP1 in regulating VEGFA levels, we explored pleural effusion VEGFA protein concentrations." (PMID 29085180, 2017). "Conforming with previous studies which mostly used peripheral blood samples, our pleural effusions study also confirmed the elevated levels of CA12, CD40, IL-6, IL-8, PD-L1, and VEGFA, proposing their potential either as biomarkers for severity and prognosis of the disease or targets for therapy." (PMID 36428847, 2022). "VEGFA prognostic data was utilised in this study for two reasons: firstly, it is a previously established adverse prognostic marker when elevated in pleural effusion, and secondly, it is used to investigate the possible functional relationship between BAP1 and VEGFA." (PMID 29085180, 2017).